IL1B (interleukin 1 beta)
Diseases named in the same sentence as IL1B in open-access papers (continued):
Sharing a sentence is not in itself a finding about the gene and the disease.
infection (continued). "The infection induces acute peritoneal recruitment of neutrophils and other innate immune cells, and the local and systemic production of proinflammatory cytokines and chemokines (IL-1β, IL-5, IL-6, TNF-α, RANTES, MIP-1β, MCP-1, KC and IL-10)." (PMID 31024025, 2019). "On the other hand, resident and recruited innate immune cells produce TNF-α and IL-1β at the site of infection, which contribute to host protection and killing mechanisms in Leishmania infection as well as may account to nociception." (PMID 31138231, 2019). "A robust innate immune response was observed in S. aureus infected femurs, with abundant levels of pro-inflammatory cytokines IL-1α, IL-1β, IL-6, and TNFα detectable as soon as one day after infection, similar to what has been reported in other musculoskeletal infection models." (PMID 30978245, 2019). "Since NLRC4 can be upregulated by lipopolysaccharide (LPS) in human neutrophils, it is conceivable that longer infections could lead to IL-1β production by neutrophils in response to P. aeruginosa." (PMID 30455194, 2019). "Caspase-1 activation in MDM mirrored the release of IL-1β, with ~35% of LPS pre-treated cells showing activated caspase-1 after 3 hours exposure to ATP, and ~70% of cells activating caspase-1 in response to a 3 hour infection with live PAO1." (PMID 30978238, 2019). "However, although neutrophils are the most prominent infiltrating cells in the early stage of infection or inflammation, the contribution of neutrophils to inflammasome activation and IL-1β production is less well understood." (PMID 31270454, 2019). "Also, because ExoU can inhibit the NLRC4 inflammasome and caspase-1, the level of IL-1β production would be expected to be higher after infection with PAO1 than after infection with PA103." (PMID 30455194, 2019). "TNF-α, IL-1β, and IL-6 are pro-inflammatory cytokines and early inflammatory markers of the body produced by LPS-induced macrophages, which can be secreted and released in large quantities under conditions of injury, infection and immune response." (PMID 31835323, 2019). "Infection of these cells with HCMV expressing a green fluorescent protein (GFP) reporter protein would then allow quantification of constitutively expressed Myc-tagged pro-IL-1β in infected versus uninfected cells using flow cytometry." (PMID 30755509, 2019). "During infection in murine macrophages, we and others showed that P. gingivalis itself did not induce the expression of the activated form of caspase-1, pyroptosis, and IL-1β, requiring a second signal for the activation of these molecules." (PMID 31341421, 2019). "However, in C57BL/6-macrophages, the levels of Il1b, Tnf, Il10, and Il6 receptor transcripts increase during infection." (PMID 30949455, 2019). "In addition, appropriate pro-inflammatory cytokines such as IL-1β and IL-6 contributes to the recovery of infection, but excessive accumulation of pro-inflammatory cytokines is known to cause chronic inflammation." (PMID 31718640, 2019). "We infected BMDMs with the 5 clones and measured IL-1β secretion upon infection." (PMID 31754185, 2019). "Although IL-1β was clearly associated with immunopathology in VVC, our study showed that additional inflammasome-dependent cytokines, such IL-1α and IL-18, were produced during infection." (PMID 31681274, 2019). "To further investigate the LRV-inhibition of the NLRP3 inflammasome in human cells, we measured IL-1β and Casp1 p20 in response to L.g.− and L.g.+ infection in cells treated with KCl (which impairs potassium efflux and activation of NLRP3) or Poly:IC (TLR3 agonist)." (PMID 31754185, 2019). "In addition, the IL-1β expression patterns were irregular in both infection groups but were significantly upregulated following infection with the virulent strain at 36 and 120 hpi (p < 0.05)." (PMID 31514454, 2019). "IL1B plays a critical role in the immune response to mycobacteria, and may increase resistance to initial infection." (PMID 30792445, 2019).
infection (continued). "Studies have shown elevated levels of IL-1β and IL-6 following infection with influenza A." (PMID 31787983, 2019). "Finally, high-levels of IL-1β were detected by ELISA in the supernatant of infected cells as early as 4 h post-infection with virulent laboratory strains of HSV-1, McKrae, and 17 and the virulent clinical isolate KOS79." (PMID 31367214, 2019). "To further understand the histological inflammatory response in the bursa, we assessed whether proinflammatory cytokines IL-1β and IL-18 were triggered during vvIBDV infection." (PMID 31632367, 2019). "PBECs released around 180 pg/ml IL-1β in response to 24 h of infection with either RV1B or RV16." (PMID 30333178, 2019). "Moreover, viral replication and the expression of IL-1β were coupled with the process of ARV-induced autophagy in the early stage of infection." (PMID 31126305, 2019). "Pyroptosis was beginning to be noticed in Salmonella and Shigella species infection, starting with the formation of the inflammasomes and leading to the maturation and release of IL-1β and IL-18 and subsequent inflammatory cascade reaction, and was exclusively dependent on caspase-1." (PMID 31814872, 2019). "IL-1β also plays a role during infections with visceralizing species of Leishmania." (PMID 31107882, 2019). "To summarize, these data suggest that IL-1β secretion occurs through two different mechanisms during infection with nga(G330D) bacteria, one dependent of and one independent of P2X7, and that IL-1β and LDH are released through separate pathways during GAS infection." (PMID 31275321, 2019). "The NLRP3 inflammasome is a multiprotein platform that is activated upon cellular infection or stress and subsequently leads to caspase-1-dependent secretion of proinflammatory cytokines, such as IL-1β and IL-18, and an inflammatory form of cell death termed as pyroptosis." (PMID 31222000, 2019). "A reduced production of TNF-α or IL-1β is related with higher bacillary burden, while a reduced production in IL-17 has been related to lower migration of T cells to the site of infection, conducting to severe scenarios of infection." (PMID 31637222, 2019). "However, infection in the presence of cathelicidin promotes caspase-1 activation, release of IL-1β and IL-18, and the influx of neutrophils." (PMID 30978238, 2019). "For instance, TNF-α triggers local containment of infection, and IL-6, as well as IL-1β, could reduce viral replication or increase antigen processing, thus promoting specific immune response." (PMID 31156641, 2019). "Indeed, increased expression of IL-1β as well as TNFα and IL-6 has been described following infection from peritoneal exudate cells and spleen cells in mice 24 hrs post-infection." (PMID 31536604, 2019). "In addition, our previous studies suggest that infection with virulent M. bovis strains induce inflammasome activation and IL-1β secretion in macrophages." (PMID 30846986, 2019). "Dam 4 exhibited an increase above baseline in IL-1β, IL-2, IL-6, IL-7, IL-15 and IL-16, and similar to Dam 2, peak levels of these cytokines were on day 14 post-infection with the exception of IL-15 (day 7); by 21 dpi, most cytokines had returned to baseline or were lower than peak levels." (PMID 30657788, 2019). "Notably, the activation of NLRP3 inflammasome significantly promoted the release of IL-1β in the supernatants of mouse kidneys at 7 days post-infection." (PMID 31474993, 2019). "Thus, we obtained 20 clinical isolates of L. braziliensis from FIOCRUZ Leishmania and assessed IL-1β secretion upon macrophage infection." (PMID 31754185, 2019). "Additionally, the vvIBDV infection triggered MIF in vivo earlier than the upregulation of IL-1β/IL-18 transcription." (PMID 31632367, 2019). "However, T. gondii infection does not activate any known human TLRs, and the signaling pathways involved in TLR-independent IL-1β production during infection, particularly in human cells, remain poorly defined." (PMID 31449558, 2019).
infection (continued). "Teleost IL-1b is also important for the host defense against pathogen infection." (PMID 31130962, 2019). "However, a study of IL-1β release in a murine S. Typhimurium in vivo infection context found that SlrP signaling inhibited IL-1β activation, contradicting this idea." (PMID 31402916, 2019). "Given that IL-1α and IL-1β production kinetics were similar and that both cell types responded similarly, subsequent experiments were only performed for IL-1β using bmDCs following 16 h of infection." (PMID 31262357, 2019). "Notably, in the ctfr−/−, il1r1−/− d/d mouse model of PA infection, neutralization of IL-1β attenuated the infection and improved bacterial clearance." (PMID 31089134, 2019). "Thus, the increased levels of the proinflammatory cytokines suggested that vvIBDV infection boosted the mRNA level of major inflammatory cytokines IL-1β and IL-18." (PMID 31632367, 2019). "Knockdown of ZFP36L1 via infection of Ad-shZFP36L1 abrogated the IL-1β-induced upregulation of these matrix-degrading enzymes, suggesting that they could be direct targets of ZFP36L1." (PMID 30622281, 2019). "In contrast, 3-MA significantly increased levels of released IL-1β upon infection with either strain, suggesting, in line with previous studies, that IL-1β or one of the inflammasome components may be targeted for autophagosomal degradation during infection." (PMID 31275321, 2019). "The prediction model of three-cytokines (IL-8, IL-1β and interferon-γ) could predict life-threatening infection with high sensitivity (training: 100.0%; validation: 100.0%) and specificity (training: 97.6%; validation: 82.8%)." (PMID 31640816, 2019). "IL-1β participates in local and systemic responses to injury, infection, and inflammation." (PMID 30583612, 2018). "Besides the beneficial role of IL-1β for clearance of infections, this cytokine has also been attributed to contribute to the severity of inflammatory diseases." (PMID 30042333, 2018). "In addition, we found that delivery of ESAT-6 into cytosol restores IL-1β production during macrophage infection with ΔESAT-6-Mtb and in uninfected macrophages enhances IL-1β production mediated by eATP via P2X7 activation." (PMID 29977244, 2018). "Macrophages were infected with H37Rv in the presence or absence of CA074-Me, a potent inhibitor of CTSB activity and in certain conditions other cathepsins, and mature IL-1β as well as cleaved caspase-1 were measured in supernatants at 6 and 24 h after infection." (PMID 29977244, 2018). "We next tested IL-1β production in infections with T. gondii." (PMID 30301855, 2018). "Interestingly, we found more IL-1α secretion (up to 100 ng/mL 48 h post-infection) than IL-1β (590 pg/mL at the same time point)." (PMID 29593716, 2018). "However, following infection, we observed significantly elevated levels of IL-1β, IL-2, IL-3, IL-5, IL-6, IL-10, IL-17A, MIP-1α, MIP-1β, KC, transforming growth factor β (TGF-β), G-CSF, and GM-CSF in HO-1−/− mice compared to HO-1+/+." (PMID 30428359, 2018). "Hence, we quantified the levels of IL-6, TNF-α, and, IL-1β in plasma obtained from intravenous infection model mice." (PMID 30251911, 2018). "Infection with other members of the Enterobacteriaceae family like Shigella and Salmonella was reported to have lethal effects in IL-1β−/− mice." (PMID 29662840, 2018). "IL-1β is a pluripotent proinflammatory cytokine that may activate a host’s defense system against infection and injury both in the peripheral immune system and in the central nervous system (CNS)." (PMID 30189852, 2018). "At 24 hours after infection, serum levels of Il-6, IL-17, IL-10, TNFα and IL1β were unchanged and while the levels of Il-6, IL-10, TNFα and IL1β increased in Ddx3xfl/y Vav-iCre relative to control animals at 72h, the difference only reached significance in the case of IL-10." (PMID 30475900, 2018).
infection (continued). "By using combinations of EP2 and EP4 receptor agonists/antagonists, we showed that while EP2 receptor signaling plays a significant role in regulating TNF-α levels, EP4 receptor stimulation seemed to be the most relevant in the PGE2-mediated secretion of IL-1β upon infection with S. Typhimurium." (PMID 30429830, 2018). "Many cell types have been identified as IL-1β producers during infection." (PMID 29891555, 2018). "Since, epithelial cells were shown to be the source of pro-inflammatory cytokines like TNF-α and IL1-β after infection with M. bovis, these cell death routes could be of importance for infected epithelial cells." (PMID 30280094, 2018). "Interleukins (IL-1β, 6, 8, 11, 12β) and interleukin receptors (IL-1R2) were up-regulated after Aeromonas hydrophila infection, which indicated that the sturgeon employed these interleukins to defense against the infection." (PMID 30560883, 2018). "Release of IL-1β was dependent on both LPS pretreatment and infection, consistent with the two-step hypothesis for NLRP3 inflammasome activation." (PMID 30154263, 2018). "Taken together, these findings suggest that IL-1β, IL-18, and caspase-1 may have different physiological function in the host response during infection." (PMID 29616195, 2018). "However, infection with type I (GT1) or type III (CTG) strain parasites was able to induce IL-1β release from LPS-treated cells, indicating that infection can activate the NLRP3 inflammasome in cells that have previously been primed." (PMID 30154263, 2018). "Here, we show that infection of human keratinocytes with HPV16 induced the secretion of IL-1β." (PMID 30089163, 2018). "This lead us to suggest that IL-1β might play the most significant role in priming naïve astrocytes for TC-83 infection and contribute to the spread of the infection in the neuronal microenvironment." (PMID 30101649, 2018). "Importantly, IL-1β was also found in significant amounts in the supernatants, particularly at 24 and 48 h post-infection (310 and 590 pg/mL, respectively)." (PMID 29593716, 2018). "The levels of IL-1β in the vaginal lavages of infected mice revealed a 10-fold increase at 7 days post-infection and continued to rise and peaked to 600 ± 95 pg/ml at 6 weeks post-infection." (PMID 29896527, 2018). "At 24 h post-infection (pi), the level of IL-1β reached its highest peak." (PMID 30013955, 2018). "In addition, not only the production of IL-1β protein but also caspase-1 activation was significantly elevated in the colon tissue of infected mice after infection." (PMID 29616195, 2018). "It has been confirmed in the hamster model for CL that infection by Leishmania generates the activation of the Nlrp3 inflammasome with the subsequent production of IL1β, and this cytokine may negatively regulate the expression of PDGF." (PMID 30333964, 2018). "The detection of a greater amount of IL-1β protein in the supernatants of AF2122-infected bMDM may relate to the release of pro-IL-1β by the higher proportion of dying cells during AF2122 infection." (PMID 29263113, 2018). "Hence, it is possible that either higher IL-1β secretion, upon C. glabrata infection, is a post-transcriptional effect, or IL-1β transcriptional induction occurs very early during infection of THP-1 cells." (PMID 29491142, 2018). "Thus, we concluded that the presence of CD8α+ DCs is essential for ISG15 to be able to boost IL-1β levels during infection." (PMID 29891555, 2018). "Interestingly, overexpression of CgYPS1, CgYPS5, and CgYPS11 in Cgyps1–11Δ cells evoked WT-like IL-1β production in THP-1 macrophages upon infection." (PMID 29491142, 2018). "The increase in the gene expression of IFN-γ, TNF-α, IL1-β, and iNOS in the liver of both groups after the infection is indicative of a systemic dissemination of S. Typhimurium which stimulated the hepatic macrophages to produce these pro-inflammatory cytokines." (PMID 30564201, 2018).
infection (continued). "Additionally, the quantities of TNF and IL-1β secreted into the tissue culture supernatant over a 24 h period following infection were comparable between genotypes." (PMID 29892302, 2018). "Contrary to our expectations, infection downregulated IL-1β, TNF-α, and IFN-γ mRNA expression in some cerebral regions, such as the OB and HC, particularly in the sham and GX mice, suggesting that strong regulatory mechanisms prevent inflammatory immune responses in these specific brain regions." (PMID 30515051, 2018). "Free ISG15 may therefore be a novel modulator of the immune response to an infection, and it remains to be investigated if other IL-1β activating infections can be influenced by ISG15." (PMID 29891555, 2018). "IL-1β is a crucial factor of host defense in response to infections and injuries." (PMID 29291748, 2018). "Similarly, we observed higher levels of IL-1β in spleens of infected BALB/c mice throughout the course of infection." (PMID 30500862, 2018). "Generally, IL-1β acts as a potent proinflammatory cytokine at the local level, triggering vasodilatation and attracting leukocytes, including monocytes and neutrophils, to sites of infection, tissue damage and stress." (PMID 29548280, 2018). "Notably, macaques infected with either challenge strain had very small amounts of IL-1β in cervicovaginal secretions, a finding consistent with the minimal inflammatory pathology evoked following primary or repeated challenge infections." (PMID 29463617, 2018). "In the current study, we observed that the infection of CSFV could promote the release of IL-1β, and this effect reached the highest value after 24 and 36 h." (PMID 30013955, 2018). "In vitro and in vivo models of infection have shown that anthropophilic species (including Trichophyton tonsurans) induce keratinocytes to secrete a limited spectrum of cytokines, mainly IL-8, IL-6, and IL-1β." (PMID 29896175, 2018). "Also in contrast to live infection, HA enhanced levels of IL-1β (n = 4) when combined with HKSP, although this was not statistically significant." (PMID 30192848, 2018). "Wild-type T. gondii infection in human CD14+ monocytes from peripheral blood caused IL-1β production, whereas infection by GRA15-KO parasites did not." (PMID 30301855, 2018). "An upregulation of il-1β has also been reported in juvenile sea bass intraperitoneally injected with V. anguillarum both at local (skin) and systemic level (spleen, head kidney) mainly during the first 8 h post-infection." (PMID 29867929, 2018). "IL-1β protein was released in response to infection with both M. bovis strains, suggesting that inflammasomes, multiprotein complexes that process the immature pro-IL-1β into the active form, are activated by infection." (PMID 29263113, 2018). "We began by infecting mice with either lethal (1e8 colony-forming unit [CFU]) or sublethal (5e7 CFU) numbers of S. aureus in the presence of AT-neutralizing monoclonal antibody (mAb) MEDI4893* and monitoring bacterial clearance and IL-1β levels in the airway 4 and 24 hr post-infection." (PMID 29490278, 2018). "Moreover, in comparison to the infection with wt, χ12253 LPS strain did lead to a lower IL-1β release from cells and decreased the level of caspase-1 cleavage into a mature form." (PMID 30429830, 2018). "This suggests that the production of IL-1β and reduction in IL-10 mediated by properdin may be required for protection against M. tuberculosis in the initial phase of infection." (PMID 29867915, 2018). "However, studies in T. gondii have demonstrated before that IL-1β an endpoint of inflammasome activation can directly mediate cellular control of infection." (PMID 30619358, 2018). "To verify that IL-1β is produced by GAS-infected keratinocytes in an SLS-dependent manner, we infected HaCaT cells with WT, SLS-deficient (ΔsagA) or sagA complemented (ΔsagA + sagA) bacteria and collected the cell culture media 6 h post-infection." (PMID 30018884, 2018).